PITHD1 (PITH domain containing 1)
Description:
Promotes megakaryocyte differentiation by up-regulating RUNX1 expression. Regulates RUNX1 expression by activating the proximal promoter of the RUNX1 gene and by enhancing the translation activity of an internal ribosome entry site (IRES) element in the RUNX1 gene.
Synonyms: C1orf128; HT014; TXNL1CL
Tractability: PROTAC: ubiquitination databases record sites on it; its protein half-life has been measured.
Gene: Protein-coding gene on chromosome 1 (23,778,393 to 23,788,232, forward strand). Ensembl gene ENSG00000057757.
Subcellular location: Cytoplasm
Gene Ontology:
Biological process: positive regulation of DNA-templated transcription; positive regulation of megakaryocyte differentiation
Cellular component: cytoplasm; nucleus; sperm cytoplasmic droplet
Genetic constraint (gnomAD): Loss-of-function variants: 3 observed, 3.62 expected, observed/expected ratio (o/e) 0.83, 90% interval 0.37 to 1.78. That is too few expected variants to judge how well the gene tolerates losing a copy. Missense variants: 120 observed, 87.54 expected, observed/expected ratio (o/e) 1.37, 90% interval 1.18 to 1.6. Synonymous variants: 66 observed, 42.7 expected, observed/expected ratio (o/e) 1.55, 90% interval 1.26 to 1.87.
Homologues: Orthologues: macaque PITHD1 (100% identical), rabbit PITHD1 (100% identical), chimpanzee PITHD1 (99% identical), guinea pig PITHD1 (99% identical), dog PITHD1 (99% identical), pig PITHD1 (99% identical), rat Pithd1 (99% identical), mouse Pithd1 (98% identical), Drosophila melanogaster CG6153 (55% identical), Caenorhabditis elegans ZK353.9 (45% identical), zebrafish pithd1 (37% identical).
Diseases named in the same sentence as PITHD1 in open-access papers:
PITHD1 is named in the same sentence as 15 diseases in open-access papers, as found by Europe PMC text mining. Sharing a sentence is not in itself a finding about the gene and the disease. The quoted sentences say what the papers report.
colorectal cancer (2 papers, 2022 to 2023). A primary or metastatic malignant neoplasm that affects the colon or rectum. "miR-590-5p has been found to suppress malignant melanoma cell growth and invasions by targeting Skp2 and downregulation of circ-PITHD1 can inhibit colorectal cancer through suppression and the miR-590-5p/HK2 axis." (PMID 37540226, 2023).
ovarian carcinoma (2 papers, 2019 to 2024). A malignant neoplasm originating from the surface ovarian epithelium. "KM plotter was used to validate the prognostic value of COL3A1, GPR158 and PITHD1 in an external ovarian cancer dataset." (PMID 31533654, 2019). "Survival analysis revealed that the RNA expression levels for the COL3A1, GPR158 and PITHD1 genes were significantly correlated with that shown on the protein expression levels, proposing them as prognostic factors for ovarian carcinoma (COL3A1) and in MC (GPR158) and CCC histotypes (PITHD1)." (PMID 31533654, 2019).
age (1 paper, 2024). A temporal measurement of the time period elapsed since an identifiable point in the life cycle of an organism. "The findings further support the idea that PITHD1 could be involved in age-related olfactory dysfunction, particularly in the context of neurodegenerative conditions like Alzheimer’s disease." (PMID 38535507, 2024).
Alzheimer disease (1 paper, 2024). A progressive, neurodegenerative disease characterized by loss of function and death of nerve cells in several areas of the brain leading to loss of cognitive function such as memory and language. "This suggests that elevated expression of PITHD1 in the olfactory tract may be specifically associated with Alzheimer’s disease and not Parkinson’s disease." (PMID 38535507, 2024).
glioma (1 paper, 2023). A benign or malignant brain and spinal cord tumor that arises from glial cells (astrocytes, oligodendrocytes, ependymal cells). "Our data show that hsa_circ_0010889 expression was significantly upregulated in glioma tissues and RT-qPCR showed that circ-PITHD1 expression increased in several glioma cell lines (SHG44, U251, T98G and LN229) when compared to normal glial HEB cell lines." (PMID 37540226, 2023).
leukemia (1 paper, 2019). A malignant (clonal) hematologic disorder, involving hematopoietic stem cells and characterized by the presence of primitive or atypical myeloid or lymphoid cells in the bone marrow and the blood. "A recent study reported that PITHD1 is downregulated in leukemia and may regulate RUNX1 expression that promotes megakaryocyte differentiation, and activates the internal ribosomal entry site." (PMID 31533654, 2019).
Obesity (1 paper, 2024). Accumulation of substantial excess body fat. "Notably, monocytes from people with obesity exhibited the most differences compared to lean donors, with only one overlap in the regulated proteins across the groups, namely PITH domain containing-protein 1 (PITHD1)." (PMID 39050851, 2024). "Thus, the role of upregulated PITHD1 in monocytes from individuals with obesity needs to be clarified in further studies." (PMID 39050851, 2024).
tumor (2 papers, 2019 to 2022). "FISH detection showcased that circ-PITHD1 expression increased in CRC tumor tissues compared to adjacent normal tissues." (PMID 36276867, 2022). "Immunohistochemistry with Ki67 staining also confirmed that circ-PITHD1 silencing inhibited Ki67 expression in tumor tissues." (PMID 36276867, 2022). "Moreover, PITHD1 was herein primarily observed in tumor nuclei." (PMID 31533654, 2019). "The outcome data suggested that circ-PITHD1 downregulations inhibited CRC proliferation and tumor growth." (PMID 36276867, 2022). "Finally, PITHD1-positivity was found in the vast majority of the CCC samples (n = 34, 92%), with positive immunostaining primarily observed in tumor cell nuclei." (PMID 31533654, 2019).
neurological disorders (1 paper, 2024). "Notably, a subset of proteins co-regulated with PITHD1 has been associated with neurological disorders such as AD and PD." (PMID 38535507, 2024).
PITHD1 also shares sentences with these, for which no sentence is quoted: clear-cell ovarian carcinoma (1 paper); infection (1); malignant melanoma (1); metastasis (1); mucinous ovarian carcinoma (1); Parkinson disease (1).